STC1 (stanniocalcin 1)
Diseases named in the same sentence as STC1 in open-access papers (continued):
Sharing a sentence is not in itself a finding about the gene and the disease.
tumor (120 papers, 2003 to 2026). "Several studies have reported that STC1 expression markedly increases within tumor tissues, which is linked to poor patient prognosis." (PMID 40741411, 2025). "STC1 expression is associated with poor postoperative survival, tumour growth and metastasis and has been proposed as a potential drug target." (PMID 40867253, 2025). "Because of the Warburg effect, STC1 causes a change from mitochondrial respiration to a more glycolytic metabolic profile, hence enhancing tumor cells’ tolerance to hypoxia and preventing them from apoptosizing." (PMID 39201771, 2024). "STC1 is considered as a regulator of calcium and phosphorus metabolism and associated with tumor progression and metastasis." (PMID 39654892, 2024). "Recently, STC1 is implicated in tumor microenvironment as a phagocytosis checkpoint, as well as regulates the immunity via macrophages." (PMID 39654892, 2024). "In recent years, some studies have found that STC1 is implicated in tumor microenvironment as a phagocytosis checkpoint." (PMID 39654892, 2024). "Stc1, recognized as a glycoprotein hormone, commands heightened expression in various tumor tissues and is intricately associated with pivotal cellular processes, encompassing cell proliferation, invasion, oxidative stress modulation, and apoptosis." (PMID 38107570, 2023). "Stanniocalcin 1 (STC1) is a secreted glycoprotein, which has been suggested as a tumor marker as its increased expression is associated with the development and/or progression of different types of malignant tumors." (PMID 37998156, 2023). "STC1 is also secreted by multiple cell types in the tumor microenvironment, including cancer cells, cancer-associated fibroblasts, macrophages, and adipocytes." (PMID 36795484, 2023). "Stc1 is known to be highly expressed in various tumor tissues and is closely associated with cancer cell proliferation, invasion, apoptosis, and vasculogenesis." (PMID 38107570, 2023). "The expression of STC1 has been associated with the development of hypoxic tumor microenvironment, which is similar to chronic inflammation." (PMID 35798563, 2022). "STC1 is a paracrine protein, and its expression is higher in cancer tissues than in adjacent tissues, which is associated with tumor growth and cancer metastasis." (PMID 36685853, 2022). "Conditioned media of STC1+PENK− cancer-associated stromal cells (isolated from a Gleason 3 tumor) were still able to induce NCCIT to down-regulate scTF and up-regulate B2M but without induction of PENK." (PMID 34911496, 2021). "Similar to the results of the epithelium, the larger tumor size (p = 0.035) seemed to be associated with weaker STC-1 expression in the stroma." (PMID 34650342, 2021). "This analysis showed amplification of tumor-associated αSMA+ cells in the fibrovascular cores (FVCs) of papillary lesions in the Stc1−/− SPK lung, which sometimes extended diffusely into solid lesions." (PMID 32579928, 2020). "For example, higher levels of circulating STC1 mRNA in serum were associated with more advanced tumour stages." (PMID 32468698, 2020). "Elevated expression of STC1 is significantly associated with the tumour grade, size, invasion and metastasis." (PMID 32468698, 2020). "Genetic analysis showed that the STC1 gene is located at the metastatic susceptibility locus of 8p, associated with tumor progression and metastases." (PMID 33156861, 2020). "Our data confirm STC1 as a secreted protein, derived from lung fibroblasts, which regulates tumor-associated macrophage (TAM) differentiation and TAF accumulation in the TME." (PMID 32579928, 2020). "Recent works have revealed the association of STC1 expressions with various pathological mechanisms and diseases phenotypes, in particular to inflammation, tumor growth and metastasis." (PMID 29467934, 2018). "Since HCC is an exemplified model of inflammation-related cancer, it represents a paradigm of studying the association between STC1 and tumor development." (PMID 26469082, 2015).
tumor (continued). "Here, we demonstrate that STC1 is associated with the metastasis of early stage ccRCC by regulating the proliferation, cell cycle, migration and invasion of tumor cells." (PMID 25740019, 2015). "Clinicopathological analysis revealed that STC1 mRNA expression was associated with Fuhrman tumor grade (P = 0.008) and overall Tumor Node Metastasis (TNM) staging (P = 0.018)." (PMID 25740019, 2015). "STC1 mRNA levels were significantly associated with Fuhrman tumor grade (P = 0.008) and overall TNM staging (P = 0.018)." (PMID 25740019, 2015). "In the present study, we first showed that overexpression of STC1 protein was associated with tumor progression (advanced pT status) and was an independent prognostic factor for OS and DFS in surgically-resected specimens of ESCC." (PMID 22200953, 2012). "As revealed by univariate Cox regression, patient age, TNM stage, and STC1 expression all exhibited significant correlation with poor prognosis, whereas upon multivariate Cox regression, age, residual tumor characteristics, and STC1 expression were independent risk factors for OS in GC patients." (PMID 40741411, 2025). "Due to clinical evidence, higher STC1 expression in tumor tissues was linked to shorter DFS and OS." (PMID 39201771, 2024). "In addition, STC1 is significantly associated with patient prognosis and influences tumor immunity by mediating six types of immune cells (CD8+T cells, CD4+T cells, neutrophils, macrophages, monocytes, and B cells) in the tumor microenvironment." (PMID 39201771, 2024). "However, some studies have indicated a tumor-suppressive role for STC1 since the loss of function of this protein disrupts normal physiological activity, particularly in gynecological malignancies." (PMID 39186548, 2024). "GSEA revealed that numerous tumor‐associated pathways were activated in the high‐STC1 group." (PMID 37543714, 2023). "High STC1 expression was associated with advanced tumor stage and poor PFS in CRC patients." (PMID 36816947, 2023). "In metastasis CRC versus controls, two pivotal negative correlated miRNA-mRNA regulatory pairs (miR-20a-5p/ FGL2 and miR-139-5p/ STC1) could be considered to associate with tumor metastasis in CRC." (PMID 38036953, 2023). "STC1 was also reported to participate in the process of epithelial-to-mesenchymal transition, which is associated with tumor invasion and the reshape of the tumor microenvironment, as well as increasing therapy resistance." (PMID 36779699, 2023). "Numerous tumor‐associated pathways were activated in the high‐STC1 group." (PMID 37543714, 2023). "However, more studies are needed to determine if ANGPTL4 and/or STC1 are the major drivers of tumor-promoting functions of cancer-associated mesothelial cells, and if these proteins play a key role in the chemoresistance and immunotherapy resistance of OvCa." (PMID 36795484, 2023). "Cancer-associated mesothelial cells secrete ANGPTL4 and STC1, which directly drive OvCa, endothelial, and monocyte cell function in the tumor microenvironment, and targeting ANGPTL4 and STC1 interferes with the tumor-promoting capabilities of cancer-associated mesothelial cells." (PMID 36795484, 2023). "We then investigated whether the proliferation of tumor cells was associated with STC-1 expression in vivo." (PMID 21672207, 2011). "Interestingly, decreased STC1 expression was linked to aggressive clinicopathologic features such as high-grade tumors, deep myometrial invasion, lymphovascular space invasion, and large tumor size." (PMID 39186548, 2024). "Moreover, some studies have indicated that in gynecological malignancies, the loss of STC1 function may impact normal physiological functions, which possibly leads to the low expression of STC1 in tumor tissues." (PMID 39654892, 2024). "Integrated analysis of RNA sequencing and NSUN2 RIP-seq identified several candidate target genes (including STC1, CDCP1, FOSL1, and Serpine1) associated with tumor invasion and neuronal interactions 22-25." (PMID 41356184, 2026).
tumor (continued). "In the relma-cel study, the expression levels of tumor-associated fibroblast markers (AP, TNC, CSPG4, PDGFRA, S100A4, ASPN, STC1, and ITGAM) were higher in the patients with PR than with CR." (PMID 39858099, 2025). "As expected, the results indicated that overexpression of STC1 increased the volume of the tumor and reduced the survival time of mice when compared with the control group (p < 0.05)." (PMID 41020346, 2025). "Expression of STC1 is modulated by hypoxia, resulting in tolerance to hypoxic conditions through reprogramming of tumor metabolism (the Warburg effect), reduction in reactive oxygen species, and antiapoptotic effects." (PMID 39807836, 2025). "STC1 expression has been demonstrated to be induced by hypoxia, a mechanism that promotes tumor angiogenesis, and to play a role in chemoresistance." (PMID 39807836, 2025). "All in all, these results suggested that STC1 significantly contributes to the malignant biological behaviors of tumor cells and resistance to TMZ." (PMID 41020346, 2025). "Substantial studies demonstrated that STC1 overexpression drives tumor aggressiveness through NOTCH1/SOX2 and TGF‐β pathways in GBM, while also contributing to angiogenesis and temozolomide (TMZ) resistance via MGMT regulation." (PMID 41020346, 2025). "This co-expression pattern indicates a potential relationship between elevated STC1 levels and an immunosuppressive tumor microenvironment in GC." (PMID 40741411, 2025). "For example, increased A20 expression reduces calreticulin (CRT) on the tumor cell surface, thereby promoting tumor growth and immune evasion through a stanniocalcin 1 (STC1)-CRT–dependent pathway." (PMID 40214497, 2025). "STC1 is a secreted glycoprotein that is aberrantly expressed in a number of tumor types and acts in an autocrine/paracrine manner to promote tumor cell viability, proliferation, solid tumor invasion, and metastasis." (PMID 39807836, 2025). "Further analysis revealed that APOD, STC1, F2R, and AGT genes are mainly expressed in tumor-associated fibroblasts." (PMID 40677704, 2025). "Stanniocalcin‐1 (STC1) is a multifunctional glycoprotein involved in calcium homeostasis and tumor progression." (PMID 41020346, 2025). "Higher STC1 expression in tumor tissues (e.g., ESCC) was correlated with decreased overall survival in humans." (PMID 41342328, 2025). "The expression and function of STC1 are often disturbed in pathological states, especially in cancer, where the expression level of STC1 is closely related to tumor progression and prognosis." (PMID 41020346, 2025). "It has been shown that a higher STC1 protein level in tumor tissues is related to a worse disease-free survival rate as well as an overall lower survival rate." (PMID 39201771, 2024). "To explore the roles of circUBA2 and STC1 in vivo, we also developed a xenograft tumour model and compared it to the group injected with control cells; xenograft tumours following the injection of STC1-silenced BGC823 cells showed a slower growth rate." (PMID 39103836, 2024). "Sevoflurane, an anesthetic, has shown favorable effects in inhibiting tumor proliferation, invasion, and migration in various tumors, including glioma, lung, colon, and EnCa, by downregulating STC1 expression." (PMID 39186548, 2024). "The TIMER database found that STC1 expression varied significantly between tumor and normal tissue in 13 different forms of cancer." (PMID 39201771, 2024). "In the review, we discussed the role of STC1 and TAMs in tumor immunity and their crosstalk, hoping to provide references for the research of STC1 in tumor immunotherapy." (PMID 39654892, 2024). "Based on the TCGA database, we chose gene set enrichment analysis (GSEA) to identify the pathways enriched in STC1 high-expressing tumours compared to those in STC1 low-expressing tumours." (PMID 39103836, 2024). "In contrast, tumor tissues have lower levels of STC1 compared to healthy tissues within bladder urothelial carcinoma (BLCA), KICH, KIRP, and THCA." (PMID 39201771, 2024).
tumor (continued). "In addition, we also conducted expression and mutation analysis on STC1 in various cancer samples and found significant differences in the expression of this gene in 13 types of malignant tumors, which is associated with the hypoxic state in the tumor microenvironment." (PMID 39201771, 2024). "In detail, STC1 participates in tumor immunity by affecting the TME, participating in the EMT, and interfering the phagocytic signals." (PMID 39654892, 2024). "One such strategy involves tumor-derived stanniocalcin-1 (STC1) interacting with calreticulin (CRT), one of the best identified damage-associated molecular patterns (DAMPS), which takes part in dead tumor cell removal because it can act as a “receptor”." (PMID 38927447, 2024). "Stanniocalcin-1 (STC1) is a glycoprotein that was first identified as a regulator of calcium homeostasis and that promotes tumor cell stemness, metastasis, proliferation, and chemoresistance." (PMID 38786045, 2024). "That is, STC1 exhibits key functions in tumor immunity by regulating the level of immune cells in TME." (PMID 39654892, 2024). "In the review, we introduced biological function and expression pattern of STC1, discussed the role of STC1 and TAMs in tumor immunity, explored how STC1 regulates the function of macrophages." (PMID 39654892, 2024). "In other words, STC1 was capable of inducing hypofunction or defect of macrophages such as migration and response to antigens, thus leading to tumor immune escape." (PMID 39654892, 2024). "In summary, the crosstalk between STC1 expression and prognosis is different across diverse tumor types." (PMID 39654892, 2024). "It was also able to influence tumor proliferation and migration, but the role of STC1 in macrophage subpopulation differentiation needs more researches to confirm." (PMID 39654892, 2024). "There are currently no clinical trials of drugs targeting STC1, but some preclinical studies have found that targeting STC1 can slow tumor progression." (PMID 39654892, 2024). "It is suggested that STC1 exhibits oncogenic properties, potentially promoting tumor progression by stimulating cell proliferation and inhibiting apoptosis." (PMID 39668832, 2024). "A significant correction was shown with both tumor diameter and tumor stage when strong STC1 expression was present." (PMID 39201771, 2024). "Elevated STC1 levels promote cancer cell proliferation, migration, invasion, and angiogenesis, thereby facilitating tumor growth and metastasis." (PMID 39668832, 2024). "In 2021, STC1 was shown to act as a phagocytic checkpoint and a TAMs function regulator, as well as participate in tumor immune escape, suggesting the interaction between STC1 and TAMs." (PMID 39654892, 2024). "In the future, more clinical samples and comprehensive analysis are needed to explore the expression of STC1 in multiple tumor tissues in well-stratified disease groups." (PMID 39654892, 2024). "In summary, STC1 affects tumor immunity by regulating immune checkpoints, affecting phagocytosis signals, impacting T cell immune response, and participating in EMT." (PMID 39654892, 2024). "Consistent with our data, elevated STC1 expression has been observed in low-grade compared with high-grade endometrioid EnCa, suggesting a potential role of STC1 as a tumor differentiation marker." (PMID 39186548, 2024). "It is clear that STC1 regulates tumor immunity by influencing TME, participating in EMT and interfering with phagocytosis signals." (PMID 39654892, 2024). "In fact, elevated STC1 in conjunction with angiopoietin-like 4 (ANGPTL4) directly modulates the tumor microenvironment, enhancing aggressive OvCa progression." (PMID 39186548, 2024). "STC1 expression in a tumour can promote tumour metastasis and invasion through different mechanisms." (PMID 38556542, 2024). "Although not previously reported in MASLD, CHRDL2 is upregulated in a range of tumor tissues including HCC49, while STC1, CTGF50, GDNF and FGF7 are all linked to hepatic fibrogenesis." (PMID 37903863, 2023).
tumor (continued). "STC1, a glycoprotein hormone, is beneficial to the proliferation, invasion and metastasis of tumor cells." (PMID 37158903, 2023). "Our data indicated that STC1 acted on the tumor microenvironment indirectly, whereas S100A4 plays a clear role in regulating the tumor microenvironment." (PMID 37400459, 2023). "The tumor’s secreted STC1 has been identified to interact with calreticulin (CRT), an “eat-me” signal, leading to reduced CRT membrane exposure." (PMID 38159261, 2023). "In this study, we confirmed that CAF-secreted STC1 promoted HCC stemness and provided evidence for an amplifying STC1-Notch1 axis in HCC stromal-tumor crosstalk." (PMID 37004088, 2023). "Previous studies have highlighted the role of Stc1 in promoting tumor cell metastasis through the activation of the PI3K/Akt signaling pathway." (PMID 38107570, 2023). "In our study, the upregulation of A20 in cancer cells promoted the growth of CRC via reducing the cell surface expression of CRT protein and facilitating tumor immune evasion in a STC1-CRT–dependent manner." (PMID 37607946, 2023). "STC1 and Notch1 signal formed a stromal-tumor amplifying feedforward signal in the TME, promoted HCC stemness, and provided new therapeutic targets for targeting both cancer cells and CAFs." (PMID 37004088, 2023). "Stc1 is highly expressed in various tumor tissues and regulates the invasion and metastasis of cancer cells by modulating the PI3K/Akt signaling pathway." (PMID 38107570, 2023). "STC1 has been considered to be involved in tumor proliferation, survival, metastasis, stem cell properties, and immune escape." (PMID 37400459, 2023). "By using publicly available TCGA databases (GEPIA), we found that HCC tumor tissues had higher expression levels of STC1 than normal liver samples." (PMID 37004088, 2023). "The overexpression of stanniocalcin-1 (STC1) in tumor cells inhibits the expression of monocyte chemokine receptors chemokine CCR2, CCR4, and colony-stimulating factor 1 receptor (CSF1R), thereby suppressing the recruitment of monocytes to the TME." (PMID 37663266, 2023). "Collectively, these findings indicated that STC1 was regulated by Notch1 at the transcriptional level, generating an amplifying STC1-Notch1 feedforward signal in tumor-stromal crosstalk." (PMID 37004088, 2023). "Recent studies have shown that targeting S100A4 has potential application value in tumor treatment, and the regulatory association between STC1 and S100A4 proposed in this study also provides theoretical support for targeting S100A4 for tumor treatment." (PMID 37400459, 2023). "SNAI1 and STC1 contribute to accelerating tumor progression in tumor growth, chemotherapy resistance, and immune environment suppression." (PMID 38033866, 2023). "Accumulating evidence had indicated that STC1 plays a crucial role in several different tumor types." (PMID 35607443, 2022). "STC1 deletion led to drastically slower cell and tumor growth, reduced intracellular ATP levels and CSC markers, and metabolically shifted STC1-deficient cells from an energetic state to a quiescent state." (PMID 36499099, 2022). "Next, we sought to confirm the tumor-promoting effect of circPOSTN/miR-219a-2-3p/STC1 axis in vivo using the xenograft tumor model." (PMID 35927233, 2022). "qPCR results showed that Pappa, Igf1 and Stc1 were only expressed in the CAFs, while Igf1r, Stc2 and Igfbp4 were expressed in both tumor cells and CAFs." (PMID 35205651, 2022). "In summary, we demonstrated that STC1 promoted tumor metastasis, lipid metabolism and DDP chemoresistance in OC cells." (PMID 35392966, 2022). "RIP assay, RNA pulldown assay, and dual-luciferase reporter assay further confirmed that circPOSTN sponged miR-219a-2-3p, restored its tumor-suppressing function, and therefore upregulated the downstream gene STC1." (PMID 35927233, 2022).